METTL25 (methyltransferase like 25)
Description:
Probable methyltransferase.
Synonyms: C12orf26; FLJ22789
Tractability: PROTAC: ubiquitination databases record sites on it.
Gene: Protein-coding gene on chromosome 12 (82,358,500 to 82,479,239, forward strand). Ensembl gene ENSG00000127720.
Subcellular location (Human Protein Atlas): Cytosol; Mitochondria; Plasma membrane
Genetic constraint (gnomAD): Loss-of-function variants: 28 observed, 34.63 expected, observed/expected ratio (o/e) 0.81, 90% interval 0.6 to 1.11. The upper end of that interval is the gene's LOEUF score, 1.11, which puts it in group 4 of 6, group 1 being the genes least tolerant of losing a copy. Missense variants: 507 observed, 447.69 expected, observed/expected ratio (o/e) 1.13, 90% interval 1.05 to 1.22. Synonymous variants: 195 observed, 170.37 expected, observed/expected ratio (o/e) 1.14, 90% interval 1.02 to 1.29.
Homologues: Orthologues: chimpanzee METTL25 (99% identical), macaque METTL25 (96% identical), dog METTL25 (85% identical), rabbit METTL25 (84% identical), pig METTL25 (84% identical), guinea pig METTL25 (77% identical), mouse Mettl25 (75% identical), rat Mettl25 (74% identical), tropical clawed frog mettl25 (48% identical), zebrafish mettl25 (45% identical), Caenorhabditis elegans F25H2.12 (16% identical), Drosophila melanogaster CG2906 (15% identical). Paralogues in human: METTL25B (20% identical).